GFAP (glial fibrillary acidic protein)
Diseases named in the same sentence as GFAP in open-access papers (continued):
Sharing a sentence is not in itself a finding about the gene and the disease.
astrocytoma (continued). "However, the survival estimates for below and above median expression of the GFAP-regulated high-malignant or low-malignant genes were significantly different for 32 of these genes in astrocytoma grade III patients." (PMID 29152145, 2017). "The GFAP-regulated high-malignant and low-malignant genes were tested for overrepresentation in a GO analysis to gain insight in the function of GFAPα and the GFAPδ/α ratio in astrocytoma." (PMID 29152145, 2017). "Therefore, we first investigated the effect of IL-17 on GFAP in human astrocytoma cell lines, by incubating U251 cells with various concentrations of IL-17 for 24 h and 100 ng/ml IL-17 for different hours." (PMID 28281545, 2017). "Focal adhesion formation is essential for cell migration and invasion and our previous studies indicated that changes in the expression of GFAP-isoforms regulate expression of plectin and integrins, genes involved in focal adhesion formation and the size of focal adhesions in astrocytoma cell lines." (PMID 29152145, 2017). "To get insight into the function of these GFAP- isoforms in astrocytoma and to investigate a potential role for GFAPα and the GFAPδ/α ratio in astrocytoma malignancy, we modulated GFAP-isoform expression in U251-MG cells by recombinant expression or by silencing with shRNAs of the isoforms." (PMID 29152145, 2017). "Thus, GFAP-isoforms have an important function in astrocytoma malignancy and the GFAP-network and GFAP alternative splicing are novel targets that await further exploration as a potential treatment for astrocytoma." (PMID 29152145, 2017). "In order to confirm the role of GFAP-isoforms and the GFAPδ/α ratio in mitosis and cell proliferation as was suggested by the GO analysis, we performed an in vitro Bromodeoxyuridine (BrdU) proliferation assay using the GFAP-modulated astrocytoma cell lines." (PMID 29152145, 2017). "To get insight into the biological processes that determine the malignancy of astrocytoma and to investigate the potential role of GFAP-isoforms in regulating these processes, we performed a differential gene expression analysis on RNAseq data of low- and high-grade astrocytoma obtained from TCGA." (PMID 29152145, 2017). "Since various members of the IF protein family are described to be involved in cell-extracellular matrix (ECM) interactions as well as in signalling and differentiation processes involved in tumour malignancy, we investigated the expression of GFAP- isoforms in astrocytoma." (PMID 29152145, 2017). "This supports a role for GFAP-isoforms and the GFAPδ/α ratio in astrocytoma malignancy." (PMID 29152145, 2017). "Similarly, a steady transfection of rat astrocytoma C6 cells with GFAP cDNA suppressed the cells proliferation and extended the cellular processes." (PMID 27494894, 2016). "In addition, transient transfection studies demonstrate that the overexpression of N-GFAP induces the formation of GFAP aggregates that also disrupt the endogenous networks of intact GFAP in transfected human astrocytoma cells." (PMID 24102621, 2013). "Moreover, the transient over-expression of GFAPdeltα in a human astrocytoma cell line, destabilizing the ratio GFAP alphα/delta, results in the formation of cytoplasmic aggregates that often collapse the endogenous GFAP networks." (PMID 22737209, 2012). "When the tumor mass was excised and examined, a spontaneous tumor progression was confirmed by the presence of prominent vascularity, presence of pseudopalisading cells and increase of GFAP which were compatible with a grade IV astrocytoma or glioblastoma multiforme." (PMID 18840301, 2008). "In addition, infection is suspected to trigger or enhance the immune response in GFAP astrocytoma." (PMID 39720731, 2024). "Previous research has demonstrated that the expression of GFAP was aberrant in astrocytoma tissue compared to normal brain tissue, with GFAP levels decreasing as with astrocytoma grading increased, so GFAP levels may serve as a novel cancer diagnostic marker." (PMID 34222466, 2021).
astrocytoma (continued). "Astrocytomas WHO grade II are GFAP positive, show limited cellular atypia, a fibrillary background, and no mitotic figures, whist astrocytomas WHO grade III have cellular atypia, although limited, are densely hypercellular and may present with abundant mitotic figures." (PMID 31938662, 2019). "In addition, regulation of these genes by a change in GFAP-isoforms could alter the biology of the tumour in such a way that it influences disease progression and survival of astrocytoma grade III patients." (PMID 29152145, 2017). "Therefore, we hypothesized that the stoichiometry of the GFAP-isoforms determines specific molecular and functional changes in astrocytoma cells related to their malignancy." (PMID 29152145, 2017). "Subsequently, modulation of GFAPα and the GFAPδ/α ratio in an astrocytoma cell model resulted in transcriptional changes, which we related to the observations in patients, and resulted in the identification of a set of high-malignant and low-malignant genes that are regulated by GFAP." (PMID 29152145, 2017). "Why certain GFAP isoforms are associated with subtypes of astrocytes, high-grade astrocytomas or other pathophysiological conditions is not known, but it has been speculated that the variable C-terminal regions affect the assembly of GFAP filaments." (PMID 22912745, 2012). "This may be associated with loss of GFAP expression in vivo, frequently found in high grade astrocytomas, although this event does not constitute a mandatory step in tumor development and it only represents the cell evolution towards an undifferentiated state." (PMID 18840301, 2008). "In primary human astrocytes and astrocytoma cells, HDAC inhibition reduces GFAP expression while increasing the ratio of the alternatively spliced GFAP isoform GFAPδ to the canonical GFAPα." (PMID 40940748, 2025). "Next, we evaluated BCAN, GFAP, and VEGF-A in Patient 46, who had stable IDH-mutant grade 4 astrocytoma post-resection and chemoradiation." (PMID 39786485, 2025). "(A) Projection light-sheet image of an FFPE-HIF-Clear mouse brain with a GFP-expressing astrocytoma xenograft (ALTS1C1 cells, see ‘Materials and methods’) stained for GFP (yellow) and GFAP (cyan)." (PMID 38775133, 2024). "Oligodendrogliomas grade 2 and 3 and astrocytomas grade 2 and 3, in general, exhibited low FABP4 and low GFAP values." (PMID 38879494, 2024). "Other groups also demonstrated significantly higher GFAP values in GBM patients compared to all other tumors, or lower-malignancy-grade astrocytoma." (PMID 33227903, 2020). "GFAP expression was significantly decreased in grade IV compared to both grade II (46%, FDR= 1.58E-10) and grade III (58%, FDR= 3.92E-7) astrocytoma." (PMID 29152145, 2017). "Pathologic grade and expressions of glial fibrillary acidic protein (GFAP), Ki67 (proliferation marker), and FMRP were determined in astrocytoma specimens from 74 patients." (PMID 27683117, 2016). "Major targets identified in our analysis, such as GFAP, CRYAB and TPIS, are major interactors of 14-3-3ζ and are powerful discriminators of low-grade astrocytoma." (PMID 25050814, 2014). "Each of these was supported by (i) the upregulation of KRT18, KRT19, E-cadherin, and downregulation of vimentin in breast carcinoma; (ii) increased levels of GFAP, MAP2, and PSD-95 in astrocytoma; and (iii) increased NeuN, GAP-43, and NF200 levels in neuroblastoma." (PMID 39859209, 2025). "As a first assessment of HIF-Clear applicability to disease models, we subjected an intact FFPE brain from an astrocytoma mouse model (see ‘Materials and methods’) to the HIF-Clear pipeline to label tumor cells (ASTS1CI-GFP positive astrocytes) and GFAP-positive astrocytes." (PMID 38775133, 2024). "As GFAP is expressed in different cells and grades of astrocytoma, it is considered a non-specific marker of glial differentiation." (PMID 35885538, 2022).
astrocytoma (continued). "The same group’s results also reiterate our findings that detectable GFAP serum levels show no dependencies with longer astrocytoma patient survival time." (PMID 33227903, 2020). "GBM38 lacked all putative stem cell markers except for GFAP, which is highly expressed in astrocytoma." (PMID 32974206, 2020). "Staining with two different antibodies for either all GFAP-isoforms or for GFAPδ shows a negative correlation of astrocytoma grade with total GFAP but a positive correlation with GFAPδ immunoreactivity." (PMID 29152145, 2017). "We conclude that not the change in GFAP per se, but the change in GFAPδ/α had the most pronounced effect on the transcriptome in astrocytoma cells." (PMID 29152145, 2017). "Although GFAP immunoreactivity is decreased with increasing astrocytoma grade, it is also known that a complete lack of all GFAP-isoforms, as in the GFAP−/− mice, is not sufficient to increase tumorigenicity." (PMID 29152145, 2017). "First, we confirmed whether GFAPδ-induced cytoplasmic collapses of GFAP also occurred in the transduced U251 cells and primary human astrocytes in SW13 human adrenal carcinoma cells and U343 astrocytoma cells." (PMID 27141937, 2016). "In the adult brain, most of glial cells express GFAP and this expression can be modified in the course of many diseases such as Alzheimer's when they become positive or even negative as in astrocytomas." (PMID 18840301, 2008). "However, the astrocytoma tissue mainly localized KMO and GFAP in the same cells; furthermore, on some astrocytoma slides, KMO immunofluorescence was found unrelated to GFAP marking, suggesting a contribution to KMO expression in tumor-infiltrated cells (lines 3–10)." (PMID 34440798, 2021). "However, a thorough analysis of the reports focusing on GFAP expression in patients with astrocytoma did not confirm the correlation between general GFAP expression and astrocytoma malignancy." (PMID 32630739, 2020). "The MMP-2 and GFAP proteins did not demonstrate any statistically significant expression differences between different malignancy grades and different IDH1 mutational status astrocytoma groups, or between the astrocytoma and healthy control groups." (PMID 33227903, 2020). "For instance, the transformed glial fibrillary acidic protein (GFAP)-positive astrocytes induced anaplastic astrocytomas (WHO grade III and IV), while the transformed glutamate/L-aspartate transporter (GLAST)-positive astrocytes formed low-grade astrocytomas (WHO grade I)." (PMID 30123112, 2018). "We should not ignore that there have been some GFAP seropositivity in disease controls (e.g., astrocytoma) and perhaps it could occur occasionally as a secondary phenomenon." (PMID 30568655, 2018). "However, with over 20% of astrocytomas formed in non-proliferative zones, it follows that either GFAP-positive NSCs have migrated to distant sites, or that tumours originate from mature astrocytes." (PMID 29759978, 2018). "Interestingly, GO analysis on all GFAP-isoform induced transcriptional changes observed in our astrocytoma cell lines revealed the cell's interaction with its environment through adhesion, ECM composition, and ECM remodelling as the major targeted modules regulated by GFAP modulation." (PMID 29152145, 2017). "Triple immunofluorescence analysis of additional patient samples revealed elevated levels of ANXA1 protein in GFAP+ cells but not in CD31+ blood vessels in GBM samples in comparison to G.2 and G.3 astrocytoma samples." (PMID 41366031, 2025). "Unlike MAPK astroblastoma and many astrocytomas, which tend to be diffusely GFAP immunoreactive, EET MN1-BEND2 shows variable, but usually only focal GFAP immunoreactivity, but like ependymoma, when present tends to be positive in perivascular pseudorosettes." (PMID 36604386, 2023). "In astrocytoma, TSPO is expressed in Iba1+ cells, but not GFAP+ astrocytes, while reactive astrocytes can contribute to the signal, in addition to reactive microglia." (PMID 31963507, 2020).
astrocytoma (continued). "Synemin was shown to co-localize with glial fibrillary acidic protein (GFAP), another type III IF protein, in astrocyte progenitor cells and astrocytoma cells, hepatic stellate cells, and non-myelin-forming Schwann cells." (PMID 32258037, 2020). "Although oncogenic KRAS-induced brain tumors reported in this study resembled astrocytoma morphologically, we cannot exclude the possibility that they are a type of undifferentiated brain tumors, such as primitive neuroectodermal tumors (PNET) which often do not express GFAP." (PMID 25644510, 2015).
amyloid (115 papers, 2008 to 2026). "GFAP, in particular, has been validated as an astrocytic marker closely associated with amyloid pathology, and has shown stability in longitudinal tracking of AD-related decline." (PMID 41180536, 2025). "Increases in plasma GFAP have been closely linked to amyloid pathology in AD35 so the treatment effect seen with gantenerumab and other amyloid plaque–removing antibodies suggests this to reflect amyloid removal." (PMID 39887500, 2025). "The results of investigations into AD pathology and LBD using plasma biomarkers suggested that abnormal levels of plasma NFL and GFAP are associated with increased amyloid levels." (PMID 40297861, 2025). "Consistent with our findings that GFAP had the second highest predictive accuracy for clinical stage and amyloid status among the biomarkers we investigated, plasma GFAP was reported to be associated with Aβ accumulation in DS27." (PMID 41213934, 2025). "Plasma GFAP, a marker of reactive astrocytes, is considered a plasma biomarker linking amyloid pathology to early tau pathology, as Aβ is associated with p-tau only in individuals with higher GFAP levels." (PMID 40640892, 2025). "In conclusion, we showed that P2X7R expression and GFAP coverage are greater in the hippocampus and EC of AD patients than in NCs and are associated with amyloid and tau pathology, in the AD brain." (PMID 41291905, 2025). "As plasma GFAP better correlates with amyloid and tau pathology than CSF GFAP, it would be ideal to investigate the underlying physiology for better performance of blood GFAP vs. CSF GFAP." (PMID 41002922, 2025). "This is supported by the fact that the association of GFAP expression and tau was attenuated when covarying for amyloid pathology." (PMID 39580758, 2024). "Across cortical regions, we found the evidence of strong associations between GFAP expression and amyloid pathology." (PMID 39580758, 2024). "The strong association of plasma GFAP with brain amyloid pathology suggests its potential utility for screening amyloid pathology, with properly adjusting for age effect recommended." (PMID 37924152, 2023). "Emerging evidence has shown reactive astrocytosis had been implicated as a potential driver or effect of AD pathological changes, and the elevated plasma GFAP levels were associated with amyloid pathology." (PMID 37065463, 2023). "Postmortem pathological associations with β‐amyloid plaques and neurofibrillary tau showed a stronger association with plasma GFAP than p‐tau181." (PMID 37000892, 2023). "To analyze the distribution of reactive astrocytes, we immunostained brain sections with antibodies against GFAP, which is strongly associated with amyloid plaque load in AD." (PMID 36209948, 2022). "In AD, recent studies showed that the plasma GFAP (pGFAP) levels are associated with amyloid pathology." (PMID 34893073, 2021). "Recent studies have shown that the elevated CSF and plasma GFAP are associated with amyloid pathology, also in cognitively unimpaired subjects." (PMID 34893073, 2021). "Interestingly, GFAP, which is usually increased in gliosis associated with amyloid, showed significantly decreased levels at 12 months in the dKI mice, similar to what we observed in the hippocampi of Unc5cKI/KI mice starting at 12 months." (PMID 40468412, 2025). "GFAP has been associated with amyloid neuropathology and suggested to have a role in early AD detection; we found GFAP concentrations were higher in AD-related syndromes, but overall had poor diagnostic performance due to a comparatively small percentage increase." (PMID 39928343, 2025). "However, an important element to consider is that CSF and plasma GFAP have been reported to be very strongly associated with markers of amyloid pathology." (PMID 40239464, 2025). "Interestingly, plasma GFAP has shown stronger associations with amyloid pathology and larger group differences than CSF GFAP." (PMID 40630394, 2025).